TLR9 (toll like receptor 9)
Diseases named in the same sentence as TLR9 in open-access papers (continued):
Sharing a sentence is not in itself a finding about the gene and the disease.
diabetes (21 papers, 2008 to 2025). "Our prior work showed IL-10-producing B regulatory cells (Bregs) protected B cell-specific TLR9-deficient NOD mice from diabetes." (PMID 38903498, 2024). "Toll-like receptor 9 (TLR9) deficiency and inhibitor decreases diabetes development by reducing proinflammatory cytokines and promoting anti-inflammatory cytokine release via enhancing CD73 expression in T cells in NOD mice." (PMID 39735551, 2024). "Bizarrely, TLR9 deficiency was found to boost glucose tolerance and insulin sensitivity in individuals with diabetes." (PMID 37998038, 2023). "TLR9 is linked to autoimmune diseases and has been associated with high-risk asthma and low-risk diabetes." (PMID 37998038, 2023). "Our microarray analyses predicted association of Toll-like receptor 9 (TLR9) with both diabetes and osteoporosis, which was the focus of this work in a murine model of type II diabetic osteoporosis (T2DOP)." (PMID 35707851, 2022). "The observation of delayed or reduced diabetes onset in TLR9-deficient mice further supports the theory." (PMID 24715890, 2014). "GSVA showed that CSF1R/H2AFV/LCK/TLR9 is associated with various pathways related to diabetes." (PMID 35187175, 2022). "In addition, a number of previous studies reported that TLR9 deficiency prevents the development of diabetes in NOD mice." (PMID 34884797, 2021). "Overexpressing CD73 with agents, such as AGT-5, Aire-overexpressing DCs, BAFFR-Fc, CD4+ peptide, ICAs, IL-2 therapies, SAgAs, sCD73, RAD51 inhibitor, TLR9 inhibitor, and VD decreases diabetes development." (PMID 39735551, 2024). "The increase in CD73-expressing immune cells is specific for TLR9 deficiency, suggesting that CD73 plays a key role in TLR9 inhibitors in reducing diabetes development." (PMID 39735551, 2024). "The relation between TLR9 and diabetes is connected via chronic inflammation, which affects the β-cell function." (PMID 37998038, 2023). "Previous studies have documented the relationship between different SNPs in the TLR9 gene in different forms of diabetes." (PMID 37998038, 2023). "A significantly lower percentage of CD19+ TLR9+ B cells (p <0.001) and CD8+ TLR9+ T cells (p = 0.016) was demonstrated in patients with newly diagnosed diabetes." (PMID 34830017, 2021). "A significantly lower percentage of CD19+ B lymphocytes (p = 0.004) and CD8+ T lymphocytes (p = 0.040) with TLR9 expression were found in the group of patients with newly diagnosed diabetes as compared to the control group." (PMID 34830017, 2021). "The percentage of CD8+ TLR9+ T cells in the group of children with newly diagnosed type 1 diabetes mellitus was lower than in children with long-term type 1 diabetes (p = 0.016)." (PMID 34830017, 2021). "The percentage of CD19+ B cells expressing TLR9 in the group with newly diagnosed type 1 diabetes mellitus compared to the control group was significantly lower (p = 0.004)." (PMID 34830017, 2021). "To investigate beta cell death, we treated Tlr9+/+ NOD and Tlr9−/− NOD mice with STZ, a chemical causing beta cell death leading to clinical diabetes." (PMID 30094467, 2018). "We have previously shown that TLR9 deficiency increases the expression levels of CD73, which is also expressed on regulatory T cells, and that TLR9-deficient mice are protected from diabetes." (PMID 30094467, 2018). "Our findings provide novel insight into the function of TLR9 beyond the immune cells and also suggest a new direction for the design of preventive and/or therapeutic strategies for diabetes." (PMID 30094467, 2018). "Our study links TLR9 and the CD140a pathway in regulating islet beta cell development and function and indicates a potential therapeutic target for diabetes prevention and/or treatment." (PMID 30094467, 2018). "The connection between TLR9 and the innate immune system may be influenced by β-cell function and diabetes." (PMID 37998038, 2023). "The relationship between TLR9 and diabetes, specifically T2DM, is well established." (PMID 37998038, 2023).
diabetes (continued). "Signaling through TLR9 changes the frequency and function of IL-10 producing B cells in NOD mice; TLR9 deficiency specifically in B cells increased IL-10 producing cells and protected against diabetes." (PMID 34616408, 2021). "Although the environment influences type 1 diabetes development, particularly in NOD mice, which are very sensitive to environmental changes, the protection from diabetes development seen in Tlr9−/− NOD mice has been consistent in our mouse colony over many years." (PMID 30094467, 2018). "However, there was no particular resistance to beta cell death in Tlr9−/− NOD mice, as diabetes onset was similar to the onset in their Tlr9+/+ NOD counterparts after STZ treatment, both at high dose and multiple low doses." (PMID 30094467, 2018). "In summary, we used a publicly available GEO dataset to perform WGCNA of immune cell infiltration in the context of diabetes and systematically identified a module related to clinical features and four hub genes (CSF1R, H2AFV, LCK, and TLR9) that may be associated with T2DM." (PMID 35187175, 2022). "Additionally, in murine TLR9-/- models it has been shown that an elevated expression of CD73 on immune cells was associated with the production of anti-inflammatory cytokines by CD4+ T cells and delayed diabetes development." (PMID 32707842, 2020). "Then, four hub genes related to the occurrence and development of diabetes were selected from the brown module: CSF1R, H2AFV, LCK, and TLR9." (PMID 35187175, 2022). "In the absence of TLR9, induced by either genetic targeting or treatment with TLR9 antagonists, which had similar effects on ontogenesis and function of beta cells, NOD mice were protected from diabetes." (PMID 30094467, 2018). "In the NOD mouse, application of a TLR9 antagonist or depletion of type 1 IFN producing pDCs resulted in inhibition of diabetogenic CD8+ T cells and delayed diabetes onset." (PMID 28861085, 2017). "In the biobreeding diabetes-resistant (BBDR) rat, KRV can induce innate immune activation and autoimmune diabetes through toll-like receptor 9 (TLR9)-signaling pathway." (PMID 19471607, 2008). "Previous studies on diabetes were with rs187084, rs352140, and rs5743836 SNPs in the TLR9 gene, and there are no direct studies." (PMID 37998038, 2023). "Thus, LCK, TLR9, CSF1R, and H2AFV are suggested to play an important role in the metabolism of patients with diabetes." (PMID 35187175, 2022). "Thus, LCK, TLR9, CSF1R, and H2AFV are suggested to play important roles in immune infiltration in subjects with diabetes." (PMID 35187175, 2022). "Furthermore, the offspring of the Tlr9+/+ NOD mice treated with TLR9 antagonist CpG-ODN had significantly delayed and overall lower incidence of diabetes than the progeny of the mice treated with control CpG-ODN." (PMID 30094467, 2018). "While TLR2 and TLR9 knockout mice show little development of diabetes, a defect of TLR3 appears to be without impact and, as we show here, deficiency in TLR4 causes enhancement of the disease process." (PMID 24086519, 2013). "We tested glucose tolerance in Tlr9−/− NOD.Scid mice and Tlr9+/+ NOD.Scid mice, neither of which develop insulitis nor diabetes." (PMID 30094467, 2018).
HCMV infection (20 papers, 2007 to 2022). "TLR9 SNP (rs 352140 G > A) seems to be the major polymorphism, contributing to HCMV infection in pregnant women." (PMID 34578364, 2021). "The association between the heterozygous variant of TLR9(rs187084) and a higher viral load has been noted in infants with HCMV infection." (PMID 34578364, 2021). "Both GG homozygous and GA heterozygous variants in TLR9 (rs352140 G > A) were found to be significantly associated with a decreased occurrence in HCMV infection among Polish pregnant women." (PMID 34578364, 2021). "Both GG homozygous and GA heterozygous variants in TLR9 2848 G > A SNP were found in our study to have been significantly associated with a decreased occurrence of HCMV infection among pregnant women." (PMID 28340580, 2017). "Complex AA variants for both TLR2 2258 and TLR9 2848 G>A polymorphisms, were estimated to be at increased risk of congenital HCMV infection (OR 11.58, 95% CI 1.19–112.59; P ≤ 0.050)." (PMID 28118851, 2017). "Regarding the outcomes presented in this report, TLR9 2848 G > A SNP seems to be the major polymorphism, contributing to HCMV infection in pregnant women during pregnancy." (PMID 28340580, 2017). "If endosomal TLR9 recognizes CpG oligonucleotides in the intracellular space, we decided to explore the correlation between TLR9 polymorphisms and HCMV infection." (PMID 28046022, 2017). "In the examined children, an association of the TLR9 SNPs rs352139 and rs352140 with HCMV infection has been confirmed." (PMID 28046022, 2017). "In recipients of allogeneic hematopoietic stem cell transplants, the HCMV infection occurred significantly more frequently among carriers of minor C allele in TLR9 -1237 T > C, as compared to the patients, carrying the T allele." (PMID 28340580, 2017). "Evaluation of the role of single nucleotide polymorphisms (SNPs), located within TLR2, TLR4 and TLR9 genes, in the development of human cytomegalovirus (HCMV) infection in pregnant women and their fetuses and neonates, was performed." (PMID 28340580, 2017). "The majority of the children in this study were also involved in earlier studies on the relationship between polymorphisms in the TLR2, TLR4, and TLR9 genes and HCMV infection." (PMID 28046022, 2017). "The previous study showed that the TLR9 2848 heterozygous status predisposes fetuses and newborns to HCMV infection and increases the risk of cytomegaly development." (PMID 27105145, 2016). "Recently, TLR4 and TLR9 polymorphisms were found to play a role in the development of congenital HCMV infection in fetuses and neonates." (PMID 27105145, 2016). "Here, we present the genotype distribution of single-nucleotide polymorphisms (SNPs) of the TLR9 gene in infants and the relationship between TLR9 polymorphisms and HCMV infection." (PMID 27105145, 2016). "The heterozygous or homozygous recessive genotypes of the TLR9 SNPs were consistently associated with a 2-fold higher risk of HCMV infection and disease development." (PMID 27105145, 2016). "Our finding that TLR9 -1486T/C and 2848C/T SNPs are associated with HCMV infection suggests an important role of TLRs and TLR-mediated signaling in the pathogenesis and outcomes of cytomegaly." (PMID 27105145, 2016). "The distribution of genotypes frequencies of TLR9 SNPs in infants and relationship between polymorphisms and the risk of HCMV infection." (PMID 27105145, 2016). "The CC genotype at TLR4 1196 SNP and the GA variant at TLR9 2848 G>A SNP were significantly associated with HCMV infection (P≤0.050)." (PMID 25844529, 2015). "The TLR9 2848 GA heterozygotic status possibly predisposes to HCMV infection, increasing the risk of congenital cytomegaly development." (PMID 25844529, 2015). "Homozygotic knockout animals for Tlr2, Tlr3 or Tlr9 are highly susceptible for CMV infection and show increased mortality rates." (PMID 25856589, 2015).
HCMV infection (continued). "At TLR9 2848 SNP, the GA heterozygotic status was associated with the HCMV infection in the overdominant model and increased the risk of congenital cytomegaly by 4.81 times." (PMID 25844529, 2015). "The GC haplotype at TLR4 SNPs and GCA variants at TLR4 and TLR9 SNPs were significantly associated with HCMV infection (P≤0.0001)." (PMID 25844529, 2015). "Associations between TLR2, TLR4, and TLR9 polymorphisms with HCMV infection have been found." (PMID 28046022, 2017). "In the current study, analysis of the allele frequencies of TLR9 SNPs showed that A (rs352139) and T (rs352140) alleles were detected more frequently in children with HCMV infection than in uninfected individuals (permutation values P = 0.003 and P = 0.03, respectively)." (PMID 28046022, 2017). "Considering TLR4 SNPs, the CC genotype in TLR4 1196 C > T SNP, GC haplotype in both analyzed TLR4 SNPs, as well as GCA multiple variants within the range of TLR4 and TLR9 2848 G > A SNPs, were found to have been correlated with congenital HCMV infection in fetuses and neonates." (PMID 28340580, 2017). "The results of our study demonstrate that TLR2 2258 G>A SNP may be an important genetic factor of the previously analyzed TLR2, TLR4 and TLR9 polymorphisms, which is involved in the development of congenital HCMV infection in Polish fetuses and neonates." (PMID 28118851, 2017). "Moreover, complex AA variants for both TLR2 2258 and TLR9 2848 G > A polymorphisms, were found to be associated with an increased risk of congenital HCMV infection." (PMID 28340580, 2017). "Our observations provide new insight into the role of TLR9 polymorphisms in HCMV infection and may suggest that the presence of the mutation in at least one allele may lead to disease development." (PMID 27105145, 2016). "For the TLR9 -1486T/C and 2848C/T SNPs, a mutation present in at least one allele may lead to HCMV infection in infants." (PMID 27105145, 2016). "Our study explored the genotype distribution of TLR9 -1237T/C (rs5743836), -1486T/C (rs187084), 1174G/A (rs352139), and 2848C/T (rs352140) SNPs in infants and the correlation between polymorphisms in the TLR9 gene and HCMV infection in infants." (PMID 27105145, 2016). "Few studies have described the association between TLR9 polymorphisms and HCMV infection." (PMID 27105145, 2016). "The role of TLR9 polymorphisms in HCMV infection is only beginning to be appreciated." (PMID 27105145, 2016). "When considered separately, TLR9 SNPs were significantly associated with risk of HCMV infection." (PMID 27105145, 2016). "Additionally, the GCA variants at TLR4 896 A>G, 1196 C>T and TLR9 2848 G>A SNPs were significantly associated with HCMV infection." (PMID 25844529, 2015). "Moreover, the presence of T-1237C polymorphism that alters TLR9 promoter activity correlates with symptomatic HCMV infection in stem cell transplants, implicating the TLR9 pathway in the recognition of and response to HCMV." (PMID 22701276, 2012). "TLR9 2848 G > A SNP may be associated with HCMV infection in pregnant women." (PMID 28340580, 2017). "Considering TLR9 SNP, the GA heterozygotes, when compared to AA and GG homozygotes, were significantly more frequent in the infected patients than in the controls, and increased the risk of HCMV infection (OR 4.81, 95% CI 1.14–20.25; P≤0.050 in the overdominant model)." (PMID 25844529, 2015). "In line with this, the same group also found association of TLR9 variants (T/C, rs187084; C/T, rs352140) with CMV disease in children and of TLR2 (A>G, rs5743708) with increased risk of congenital HCMV infection in Polish fetuses and neonates." (PMID 36016941, 2022). "As far as TLR9 SNPs are concerned, we selected SNP (rs352140), which was involved in maternal HCMV infection in Polish pregnant women and cCMV infection in Polish newborn infants." (PMID 34578364, 2021).
HCMV infection (continued). "So far, it has been the first study to reveal a really significant role of TLR9 2848 G > A SNP in the occurrence of HCMV infection in pregnant women." (PMID 28340580, 2017). "Other studies also showed the SNPs located in TLR2, as well as in TLR3, TLR4, TLR7 and TLR9 genes, to be contributing to HCMV infection." (PMID 28118851, 2017). "In human monocytoid THP1 cells and foreskin fibroblasts, TLR9 was determined to induce the expression of TNF-α at 1 h after HCMV infection." (PMID 28340580, 2017). "The inhibited cytokine expression, observed after treatment of pDCs with CpG, agonists for TLR7 and TLR9, suggested an involvement of the reported TLRs in the development of HCMV infection." (PMID 28340580, 2017). "The outcomes presented in the current study show that TLR9 2848 G > A SNP seems to be involved in the occurrence of HCMV infection in pregnant women." (PMID 28340580, 2017). "It was previously demonstrated that the TLR9–1486 and 2848 polymorphisms as well as the TLR2 1350 SNP are associated with an enhanced risk of HCMV infection and disease in newborns and infants." (PMID 28046022, 2017). "Considering the role of TLR9 SNP in HCMV infection, the TT homozygotic status in TLR9 -1237 T > C SNP was reported to have been correlated with a decreased risk of the infection in HCMV-seropositive kidney transplant recipients." (PMID 28340580, 2017). "GG homozygotic and GA heterozygotic status in TLR9 2848 G > A SNP decreased significantly the occurrence of HCMV infection (OR 0.44 95% CI 0.21–0.94 in the dominant model, P ≤ 0.050)." (PMID 28340580, 2017). "A study performed for neonatal human fibroblasts, showed some involvement of TLR9 in the development of HCMV infection as well." (PMID 28340580, 2017). "Among various TLR2, TLR4 and TLR9 polymorphisms, TLR2 2258 G>A SNP seems to be an important factor associated with increased risk of congenital HCMV infection in Polish fetuses and neonates." (PMID 28118851, 2017). "We found an increased frequency of heterozygous genotypes TLR9 -1486T/C and 2848C/T in infants with HCMV infection compared with uninfected cases." (PMID 27105145, 2016). "In conclusion, it was found that the heterozygous genotypes of TLR9 -1486T/C and 2848C/T SNPs as well as the homozygous AA genotype of the intronic 1174G/A SNP were prevalent in infants with HCMV infection." (PMID 27105145, 2016). "In this study, we demonstrated that the heterozygous genotype of TLR9 -1486T/C and 2848C/T occurred more frequently in infants with HCMV infection than in uninfected cases." (PMID 27105145, 2016). "Four polymorphisms (-1237T/C, rs5743836; -1486T/C, rs187084; 1174G/A, rs352139; and 2848C/T, rs352140) in the TLR9 gene were genotyped in 72 infants with symptomatic HCMV infection and 70 healthy individuals." (PMID 27105145, 2016). "TLR9 -1237T/C, -1486T/C, 1174G/A, and 2848C/T SNPs were typed in 142 infants, including the 72 subjects with HCMV infection." (PMID 27105145, 2016). "Considering the activity of TLR9 in the development of HCMV infection, the involvement of GA heterozygotic status at TLR9 2848 SNP seems to be possible in an altered response against the virus, including the changed expression of proinflammatory cytokines." (PMID 25844529, 2015). "So far, no other study has reported similar analyses of the influence of multiple TLR4 and TLR9 SNPs on the congenital HCMV infection, although it seems to be an important trend in the search for the related molecular markers." (PMID 25844529, 2015). "Tabeta and colleagues reported that during mouse cytomegalovirus infection deficiency of TLR3 and TLR9 increases the infection due to reduced type I IFN secretion and NK cell activation." (PMID 25539593, 2014). "Such overlapping effects between TLR7 and TLR9 have been observed during murine cytomegalovirus infection." (PMID 21253574, 2011).